MAVS (mitochondrial antiviral signaling protein)
Diseases named in the same sentence as MAVS in open-access papers (continued):
Sharing a sentence is not in itself a finding about the gene and the disease.
viral infection (continued). "Confocal microscopy showed that CNTN1 and USP25 colocalized and dispersed throughout the cytoplasm without virus infection, which had a partial association with MAVS." (PMID 35171955, 2022). "Substantial evidence indicated that the autophagy is not only a process of degradation of harmful components and intermodulates but also participates in MAVS‐mediated antiviral signaling, suggesting that autophagy is an important host defense mechanism against viral infection." (PMID 37521851, 2022). "RNF5 associates with STING and ubiquitinates STING at Lys150 for K48-linked ubiquitination and proteasomal degradation after viral infection, denoting the important role of RNF5 in dampening virus-triggered IFN-I induction by targeting both MAVS and STING degradation." (PMID 36042206, 2022). "Furthermore, another HECT-type E3 (AIP4) is recruited by PCBP2 to promote the degradation of MAVS following virus infection." (PMID 36498930, 2022). "Therefore, the data suggest that the phosphorylation of STAT2 Y690 at the early stage of viral infection was mainly regulated through the RIG-I/MAVS signaling." (PMID 36148221, 2022). "MAVS can be regulated at post-translational level during viral infection." (PMID 36028484, 2022). "Furthermore, MAVS was shown to directly interact with procaspase-8, forming so-called MAVS-death-inducing signaling complexes upon viral infection." (PMID 35436994, 2022). "Hence, efficient activation of MAVS is crucial for mediating the host innate immunity against viral infection and must be tightly regulated to avoid potentially harmful tissue damage." (PMID 36028484, 2022). "In response to viral infections, viral RNA can be sensed by the cytosolic RNA sensors retinoic acid-inducible gene I (RIG-I) and/or melanoma differentiation-associated protein 5 (MDA5) and activate NF-κB through interaction with MAVS." (PMID 34194436, 2021). "Thus, the formation of MAVS aggregates plays a key role in the propagation of the antiviral signaling cascade and is tightly regulated by viral infection." (PMID 34578357, 2021). "In addition, focal adhesion kinase (FAK) interacts with MAVS at the mitochondrial membrane in a viral infection-dependent manner to potentiate MAVS-mediated signaling via a kinase-independent mechanism." (PMID 34782737, 2021). "In addition, the increasing trend of virus proliferation curve from 24 to 120 h after aMPV/C infection also indirectly indicates that virus infection induces the decrease in MAVS." (PMID 34696420, 2021). "Following viral infection, USP18 is enriched in mitochondria and promotes the mitochondrial translocation of TRIM31 from the cytoplasm and interaction between TRIM31 and MAVS, consequently enhancing TRIM31-mediated K63-linked polyubiquitination and subsequent aggregation of MAVS." (PMID 34016972, 2021). "We next tested whether TFG could be involved in the organization of MAVS signalosome networks upon viral infection." (PMID 33411856, 2021). "In addition to these studies, we previously showed that the ER-to-Golgi vesicular transport system serves as an organizing membrane-rich platform allowing the proper positioning of TRAF3 with MAVS onto the mitochondria network following virus infection." (PMID 33411856, 2021). "Targeting MAVS for viral immune evasion has also been reported during a set of virus infections." (PMID 33593967, 2021). "However, only exposure to a 5-Gy dose dramatically increased MAVS cleavage (52kDa band), shown to be induced by dsRNA during viral infection." (PMID 33556144, 2021). "Since autophagy and apoptosis are significantly induced in the late stage of viral infection and participate in viral replication, it may indirectly affect the degradation of MAVS induced by aMPV/C infection." (PMID 34696420, 2021). "Viral infection causes the RIG-I-like receptor (RLR) to recognize pathogen-derived dsRNA and then becomes activated to promote prion-like aggregation and activation of MAVS." (PMID 34880843, 2021).
viral infection (continued). "Crucially, it is the response of the Calu‐3 cells to virus infection, via RNA sensing, that drives macrophage activation in these experiments, evidenced by suppression of activation after either MAVS depletion or NF‐κB (TPCA‐1) or JAK inhibition (Ruxolitinib) in the infected Calu‐3 cells." (PMID 34101213, 2021). "To investigate the mechanism by which DNA damage induces A3A expression, we first asked whether the RIG-I/MAVS pathway is required to stimulate A3A expression, as found after 3p-hpRNA transfection or viral infection." (PMID 34389714, 2021). "Several studies have now demonstrated that MAVS could be modified by ubiquitination during viral infection." (PMID 33577621, 2021). "We overexpressed MAVS in HEK293 cells to induce a condition that mimicked viral infection." (PMID 33603735, 2020). "It was also reported that the MAVS overexpression causes the induction of IFN proteins without virus infection, possibly by auto-activation." (PMID 33177519, 2020). "Notably, the induction of NOXA during viral infection is controlled in part by MAVS —a key regulator of antiviral signaling and another substrate of MARCH5." (PMID 32094511, 2020). "Upon viral infection, the E3 ligase TRIM31 catalyzes K63-linked ubiquitination and promotes aggregation and activation of MAVS which is prevented by the Otubain family deubiquitinating enzyme YOD1, and TRIM21 induces K27-linked ubiquitination of MAVS to promote the recruitment of TBK1 to MAVS18–20." (PMID 33139700, 2020). "Different truncated Mfn2 and MAVS were overexpressed in HEK293T cells followed by virus infection." (PMID 32943610, 2020). "However, upregulation of MAVS expression during viral infection overcomes the PPM1A-mediated block in signaling and serves as a threshold for activation of antiviral signaling." (PMID 32536927, 2020). "Liu and colleagues reported YOD1-mediated K63-linked deubiquitination could activate an innate antiviral immune response against viral infection, and the aggregation of MAVS." (PMID 33343629, 2020). "Several molecules like NLRX1 and DUBs regulate RIG-I binding to MAVS at the mitochondria or directly target MAVS for degradation, thus acting as a counterbalance to prevent overproduction of Type I Interferons during a persistent viral infection." (PMID 32983015, 2020). "However, MAVS/IFN-β signaling by virus infection was inhibited by stress/CORT, evidenced by decreased protein level of MAVS, p-IRF3, and IFN-β, as well as declined gene level of IFN-β." (PMID 32943610, 2020). "Interestingly, downregulation of glucose metabolism and lactate-mediated repression of MAVS occurs only in the early stages of viral infection." (PMID 32536927, 2020). "The diversity of E3 ubiquitin ligase involved in MAVS degradation suggests that they could provide more targets for the treatment of viral infections." (PMID 32536927, 2020). "In addition, MAVS-M142 cannot prevent the aggregation of FL MAVS during viral infection, but can block the production of IFN after MAVS-M142 binding to TRAF." (PMID 32536927, 2020). "During virus infection, the viruses could interact with host proteins to dampen the functional assembly of the MAVS complex." (PMID 31717991, 2019). "DDX3 is a well-known example, being suspected of being a transcription factor for IFN-β, associating with spliceosomes and the stress-induced p-bodies to influence mRNA splicing and decay, respectively, and interacting with the MAVS complex during viral infection conditions." (PMID 31379819, 2019). "After infection, viral RNAs are sensed by the RLRs in the cytosol and through the mitochondrial adaptor MAVS, they engaged a signaling pathway leading to type I IFNs production and these cytokines combat viral infection for instance by preventing virus replication." (PMID 31024004, 2019). "However, how viral infection induces some common mechanisms to negatively regulate the stability of MAVS/TRAF3/TRAF6 signalosome remains to be illuminated." (PMID 29734366, 2018).
viral infection (continued). "Since several studies have shown that TRIM25 migrates to the mitochondria upon viral infection to interact with MAVS, the interaction between MAVS and NS1 might be a result of the interaction between NS1 and TRIM25." (PMID 30558248, 2018). "However, until this point there are few studies that clearly analyzed the dynamics of downregulation of MAVS/TRAF3/TRAF6 proteins during viral infection." (PMID 29734366, 2018). "Therefore, we think that at the late stage of viral infection, more signaling molecules take part in the regulation of the MAVS/TRAF3/TRAF6 signalosome, and finally result in the right balance of RLR-MAVS-IFNs signaling." (PMID 29734366, 2018). "First, to determine whether virus infection triggers diverse species of MAVS polymers (i.e., oligomer intermediates and high MW aggregates), A549 cells were infected with SeV at 10 HAU/106 cells for 4 h." (PMID 29385716, 2018). "This accumulation of MAVS is the result of MAVS being synthesized in response to viral infection." (PMID 28883463, 2017). "Deficiency in any individual one of these genes showed marginal effect on MAVS aggregation on virus infection, suggesting they might play redundant roles." (PMID 28469175, 2017). "A future challenge is to develop new drugs that regulate the protein modification of RIG-I and MAVS, which may help to treat virus infections." (PMID 28594325, 2017). "Remarkably, when Ube2Ds or Ube2N was ectopically expressed in si-Ube2D3/Ube2N−/− cells, MAVS aggregation could be fully restored on virus infection, and IFN induction was also rescued." (PMID 28469175, 2017). "It has been demonstrated that the bridges linking the ER and the mitochondria are composed of high-molecular weight protein complexes, and that upon virus infection, MAVS aggregates to form a prion-like structure that is required for the recruitment of downstream TRAF molecules." (PMID 28848563, 2017). "We next explored whether these E2s are indeed required for RIG-I and MAVS activation in cells on virus infection." (PMID 28469175, 2017). "Similar to previous studies showing constitutive interaction between RIG-I and MAVS in NLRX1-deficient cells, we found that NLRX1 bound to MAVS in the absence of virus infection." (PMID 28542569, 2017). "Indeed, aggregation of endogenous MAVS upon virus infection was largely inhibited when MAVS-TM is expressed transiently." (PMID 28607490, 2017). "Nevertheless, we could observe colocalization of TIM23 with LC3 puncta in a small portion of mitochondria in the MAVS+/+ cells, when compared with that in MAVS−/− cells upon VSV virus infection." (PMID 27551434, 2016). "Previously, it has been reported that MAVS expression could be downregulated by virus infection via ubiquitin-proteasome-dependent pathways and mRNA instability." (PMID 27705941, 2016). "To assess the risk of viral infection based on MAVS variation, we tested the effects of twelve non-synonymous MAVS coding-region SNPs from the National Center for Biotechnology Information (NCBI) database that result in amino acid substitutions." (PMID 26954674, 2016). "Interestingly, it had been showed that caspase activation induced by virus infection resulted in MAVS cleavage and consequent inhibition of interferon production, but did not result in increased virus titers." (PMID 27610098, 2016). "Though PC was described mainly located in mitochondria, in this study, we discovered that PC could translocate to cytoplasm in response to viral infection, and the interaction between PC and MAVS occurs on mitochondria." (PMID 26906558, 2016). "Moreover, RIG-1 is recruited to the MAM-resident MAVS upon virus infection, leading to the activation of RIG-I-MAVS signaling." (PMID 25941664, 2015). "The pseudoatomic model for the MAVS CARD filaments from our cryoEM study suggests that after viral infection, activated MAVS molecules on the mitochondrial surface interact with each other at both the intra- and inter-strand interfaces between their CARD domains." (PMID 24569476, 2014).
viral infection (continued). "Thus, in myeloid cells, viral infection triggers signaling through MAVS to induce proinflammatory cytokines that can result in sepsis and organ damage." (PMID 24743949, 2014). "Importantly, MAVS binds to the TRAF proteins in a manner that depends on virus infection and MAVS polymerization." (PMID 23951545, 2013). "The RIG-I/MAVS pathway plays an essential role in initiating cellular signals leading to the activation of transcription factors and subsequent induction of inflammatory/immune and antiviral mediators in response to viral infections." (PMID 23626834, 2013). "Upon virus infection, RIG-I undergoes Lys63-linked polyubiquitination by the E3 ligase TRIM25 to trigger the binding with the mitochondrial adaptor IPS-1 (also known as VISA, Cardif, or MAVS) via CARD-CARD interactions found in both proteins." (PMID 23308279, 2013). "Here we demonstrate for the first time that MAVS undergoes extensive tyrosine phosphorylation upon viral infection, indicating that MAVS phosphorylation might play an important role in MAVS function." (PMID 22844514, 2012). "However, this possible mechanism of action requires further investigation to determine how TRAF3 is recruited to the mitochondrial adaptor protein MAVS upon viral infection." (PMID 22792062, 2012). "Finally, introduction of exogenous MAVS into CVB3 pre-infected cells also restricted viral infection efficiently by greatly up-regulating IFNs." (PMID 23249700, 2012). "Upon virus infection, TANK has been shown to associate with MAVS as well as TRAF3 and TBK1." (PMID 20161788, 2010). "Moreover, MAVS C79F lost its ability to trigger the activation of type I IFN signaling under SeV or IC poly(I:C) treatment conditions, suggesting that SLE patients with MAVS C79F are at increased risk of viral infection." (PMID 39621307, 2024). "Finally, DDX11 interacted with MAVS, and this interaction was increased after viral infection." (PMID 39470258, 2024). "Therefore, this new understanding of MAVS aggregation might provide potential targets for drug development against viral infections and autoimmune diseases." (PMID 39621307, 2024). "Compared to current methods of viral infection detection, like viral protein expression or MAVS cleavage by immunoblotting, this method could reveal infection much earlier and more importantly, this provides a method that could monitor viral infection in live cells at single-cell level." (PMID 37243150, 2023). "Upon viral infection, the CARD domain undergoes tripartite motif containing 25–mediated Lys63 (K63)-linked polyubiquitination, which allows it to interact with the CARD domain of mitochondrial antiviral signaling protein (MAVS), which is anchored to the outer mitochondrial membrane." (PMID 38043800, 2023). "As viral infection could cause mitochondrial fusion fission imbalance, and MFN1 is a GTPase protein located on the outer membrane of mitochondria, its expression is increased in HCMV infection, which may be involved in the localization of MAVS." (PMID 36939338, 2023). "In addition, SIRT5 catalyzed K7 desuccinylation of mitochondrial antiviral signaling (MAVS) protein, resulting in reduction of aggregation and activity of MAVS after viral infection, the impairment of type I interferon production, and antiviral gene expression." (PMID 34913133, 2022). "In addition, the spontaneous aggregation of MAVS could induce ROS production and Bcl-2 interacting protein 3 like (BNIP3L, also named NIX)-mediated autophagic clearance of MAVS aggregates in response to viral infection." (PMID 35844503, 2022). "Therefore, MAVS-dependent pathogenesis in response to viral infection may be more nuanced than simply limited to hepatotropic viruses." (PMID 35587473, 2022). "Notably, PRMT9-mediated suppression of MAVS autoactivation was broken during viral infection." (PMID 36028484, 2022). "Of note, MFN1 may play an opposite role by interacting with MAVS during viral infection." (PMID 34482801, 2021).
viral infection (continued). "Thus, long noncoding RNAs may also inhibit viral replication by disrupting HK2, voltage-dependent anion channel (VDAC), and MAVS ternary complex to inhibit glycolysis in viral infection." (PMID 34917069, 2021). "In addition to MAVS cleavage, some viral infections mediate proteasome degradation of MAVS." (PMID 34696420, 2021). "During viral infection, the cellular localization of MAVS may change." (PMID 33807534, 2021). "However, during viral infection, binding of activated RIG-I to MAVS causes dissociation of HK2, leading to a reduction in glycolysis and lactate production, attenuation of lactate-mediated MAVS inhibition, and upregulation of downstream signaling for IFN production." (PMID 32536927, 2020). "During viral infection, NLRX1 was also demonstrated to negatively regulate RIG-I activation through interaction with poly(rC) binding protein 2 (PCBP2) and mitochondrial anti-viral signaling (MAVS) via its NACHT domain to cause lysine 48 (K48)-linked polyubiquitination and degradation of MAVS." (PMID 32012730, 2020). "However, RIG-I-MAVS signaling does not seem to play a critical role in the defense against viral infection; survival and adaptive immune responses against the influenza virus were unchanged in MAVS-deficient mice relative to wild-type controls." (PMID 32375274, 2020). "Combined with our previous finding that NF-κB P65 could directly mediate the transcription of CXCL16 in keratinocytes through directly binding to the promotor of CXCL1645, we draw a conclusion that CXCL16 is mainly elaborated by IRF3 and NF-κB in the downstream of MAVS under virus infection." (PMID 32532953, 2020). "However, with viral infections, virus-infected cell elimination may occur by inhibiting the expression of cell adhesion molecules via the MAVS-signalling cascade, and following the induction of virus-induced apoptosis in the infected cells." (PMID 32317718, 2020). "Our results confirmed that the relative amount of UDP-N-acetylglucosamine increased during the first replication cycle of the virus, which may increase the glycosylation of MAVS, helping it to form prion-like aggregates to activate an antiviral response in innate immunity after viral infection." (PMID 31683654, 2019). "Thus, the interaction between RIG-IN and MAVS upon virus infection was analyzed." (PMID 30558248, 2018). "The level of microRNA concentration is reversed to the ΔCT, so it is suggesting that this miR-150-5p is positively correlated with MAVS 70 kD and might facilitate anti-viral activity during viral infection and this might be reflected by elevation of CRP levels clinically." (PMID 30105262, 2018). "Therefore, we sought to evaluate whether virus infection induces multiple polymerization states of MAVS." (PMID 29385716, 2018). "In addition, recombinant sumo-MAVS-ΔTM was purified to contain two populations, including monomeric form and prion-like aggregated form, resembling endogenous MAVS functionally before and after viral infection respectively." (PMID 28607490, 2017). "Although we failed to assess the risk of viral infection based on MAVS variations, we speculate that such variations may result in serious immune-related diseases." (PMID 26954674, 2016). "While PKR may be capable of functioning independently from MDA5 when activated in an RNA-independent manner (8 h), its ability to signal to MAVS during viral infection is augmented in an MDA5-dependent manner, suggesting that PKR acts ‘downstream’ of MDA5 and ‘upstream’ of MAVS." (PMID 26939124, 2016). "Wild-type MAVS could only induce IL-6 expression in response to Sendai virus infection, while MAVS (Δaa-141–160/Δaa-201–350/Δaa-401–450) induced IL-6 expression independently of virus infection." (PMID 26183716, 2015).